IFNG (interferon gamma)
Diseases named in the same sentence as IFNG in open-access papers (continued):
Sharing a sentence is not in itself a finding about the gene and the disease.
infection (continued). "TNF and IFNγ had opposite effects on IL-6 production, with IFNγ neutralization resulting in a significant increase in IL-6, with concentrations similar to that of a primary Lm-gp61 infection." (PMID 29438281, 2018). "These experiments reveal that the effect of IFNγ on bystander cells is critical to limit spread of a primary infection." (PMID 29855501, 2018). "Despite the presence of M1 macrophages during Arg1/M2 blockade and M2 macrophages during IFNγ/M1 blockade, bacterial control was suppressed in Stat2−/− mice during super-infection." (PMID 30337919, 2018). "Based on the kinetics of IFNγ and IL-17 production by γδ T cells, we tested the function of γδ T cell subset in the ensuing immune response against Cm infection." (PMID 29670466, 2018). "At 3 days after intraperitoneal VACV infection, the frequency of IFNγ+CD4+ T-cells in mesenteric lymph nodes and peritoneal exudate was lower in Lmna−/− mice than in WT mice." (PMID 29311549, 2018). "As early as 2 DPI, we measured interferon-gamma (IFNγ) production indicative of an active infection." (PMID 29785929, 2018). "In this case, re-challenge at distal sites from the original infection results in rapid production of IFNγ and recruitment of inflammatory monocytes in a CXCR3 dependent manner." (PMID 30386342, 2018). "Further, IFNγ-secreting CD4+ T cells were detected on day 6, day 10 and day 14 post infection (p.i.) using an enzyme linked immunospot assay (Elispot) under ex vivo stimulation with heat-inactivated HSV-1 (Heat-iHSV) for 24–48 hours." (PMID 30531962, 2018). "The male mice had increased lung bacterial loads, increased iNOS, IFNγ, IL-1α/β, and IL-6 production early and late in infection, and higher levels of various inflammatory chemokines, all of which correlated with increased bacterial burden." (PMID 30619306, 2018). "IFNγ plays a key role in the induction and maintenance of Th1 responses and infection of neonatal mice with recombinant RSV expressing IFNγ prevents enhanced disease upon re-infection." (PMID 29915592, 2018). "Upon infection, the cytokine interferon gamma (IFNγ) is produced and elicits host defence mechanisms able to recognise the PV and destroy the parasite." (PMID 29510761, 2018). "Here we show that lamin A/C expression augments CD4+ T-cell Th1 differentiation in response to pathogen infection by regulating T-bet transcription factor expression and IFNγ production." (PMID 29311549, 2018). "A T helper type 1 (Th1) immune response characterized by the production of interferon-gamma (IFN-γ) is protective against experimental infection with T. cruzi through the induction of classically activated macrophages (CAM)." (PMID 30555475, 2018). "Surprisingly, this neonatal infection resulted in the production of IFNγ along with increases in inflammatory cytokines and chemokines, including TNFα, CXCL1, and CXCL2 in the lungs." (PMID 29915592, 2018). "Their early transcriptional response to infection was dominated by interferon gamma and, unexpectedly, type I interferon response genes, which led to functional studies demonstrating that type I interferon was responsible for suppressed CD4 T-cell function." (PMID 29695497, 2018). "Although IFNγ’s role in contraction of T-cell responses after the resolution of infections is well defined, its role in neutrophil contraction has been less clear." (PMID 29352287, 2018). "In contrast, the infection alone showed an inadequate drop in IFNγ, IL-2, and IL-10 levels over the course of infection." (PMID 29740435, 2018). "Axons in the N compartment were pretreated with IFNβ or IFNγ for 24 h prior to infection with RABV P-mCherry." (PMID 30028873, 2018). "Most recently, a comparative cytokine analysis using different T. evansi infections confirmed the induction of IFNγ in all infections." (PMID 30333827, 2018).
infection (continued). "This effector function extended beyond the “early” (150–250 dpi) chronic phase, as CD8+ T cells in both the muscle and spleen retained the capacity to respond to parasite epitope injection with the production of IFNγ at >700 days post infection." (PMID 30419010, 2018). "Gene expression studies also revealed higher levels of IFNγ as well as IL-10 in the inflamed footpad during enhanced infection." (PMID 29382880, 2018). "The PD1/PDL1 blockade has been found to restore both CD4+ and CD8+ T cells function, especially in terms of high IFNγ and low IL-10 production, in L. infantum and L. major infections." (PMID 29915577, 2018). "A possible model to explain our collective results following PE243 infection is the one in which CD4+ TFH cells induce the differentiation of B cells into GC-B cells in a mechanism dependent of IFNγ." (PMID 30087337, 2018). "In contrast, all MIIG transgene positive mice, which possessed macrophages that were insensitive to IFNγ, remained resistant to infection following IFNγ treatment." (PMID 30283457, 2018). "Respiratory infections such as influenza induce the generation Th1 TRM cells that can be recalled to produce IFNγ and provide protection against heterotypic infections." (PMID 30386342, 2018). "Early IFNγ production requires IL-12, as IL-12 depletion leads to abrogated IFNγ levels and reduced resistance to infection." (PMID 30475900, 2018). "We tested this by comparing the nucleo-cytoplasmic distribution of pSTAT1 at 24 hpi, when IFNγ was added to cells concurrent with infection, or 24 hours prior to infection and then maintained during infection." (PMID 29855501, 2018). "During infection, pro-inflammatory cytokines such as interleukin 12, interferon gamma (IFNγ), and tumor necrosis factor alpha (TNFα) are essential for parasite killing." (PMID 29867974, 2018). "γδ T cells are also a direct and potent source of critical inflammatory cytokines like IFNγ, TNFα and IL-17A in many pathological contexts, including infection, autoimmune disease and cancer." (PMID 30538697, 2018). "It is also possible that other reactive oxygen species are involved in increased IFNγ-mediated bacterial clearance in Stat2−/− mice during super-infection." (PMID 30337919, 2018). "The induction of cellular immune responses upon infection among the different vaccine groups was checked at different time points post-challenge using an IFNγ capture-ELISA." (PMID 29467018, 2018). "At 8-weeks post-infection ferrets displayed a mixed Th1/Th2 cytokine profile, with increased transcription of both IFNγ and IL-4." (PMID 29601572, 2018). "IFN-I blockade led to abolishment of NOS2 function and reduced cytotoxic activity and IFNγ production by NK cells at early stages of infection." (PMID 28154565, 2017). "The cytokine cascade events following B. pseudomallei infection has been studied in several animal models and show an up regulated mRNA expression of inflammatory cytokines such as IL6, IL12, IL10, IFNγ, TNFα and IL1β within 72 hours of infection." (PMID 28628607, 2017). "Birinapant treatment enhanced IFNγ-induced expression of iNOS synergistically in infected cells (M1 proteins) at 48 h post infection time interval which was accompanied with the upregulating XIAP proteins." (PMID 29375545, 2017). "TNF-α is a primary signaling molecule in systemic inflammatory reactions and is a vital component of the acute phase response; IFNγ is a key signaling molecule in clearance of intracellular pathogen infections." (PMID 29375568, 2017). "When CD8+ T cells were eliminated, CD4+ T cell depletion increased virus titers and AM infection significantly more than did IFNγ neutralization." (PMID 28394921, 2017). "Intra-peritoneal administration of RU486 partially rescued the number of thymocytes in BL/6 mice and the extent of rescue was enhanced in Ifnγ−/− mice upon infection." (PMID 28091621, 2017).
infection (continued). "Among those tested the pro-inflammatory mediators IL1α, IL1β, IFNγ and IL-6 and numerous chemokines were substantially elevated in male lungs as early as 21 days post infection." (PMID 28887521, 2017). "Second, RU486 treatment did not rescue the depletion of CD24hi/intCD3hi SP cells in Ifnγ−/− mice, indicating that Ifnγ produced during infection slowed the maturation and/or increased the survival of these thymocytes." (PMID 28091621, 2017). "The expression of IFNγ increased after the L2-MHV3 infection in WT mice, whereas less profound induction was observed in IL-33 KO mice." (PMID 28607531, 2017). "CD8+ T-cells also produce IFNγ in response to infection and potentially lyse Cryptosporidium spp.-infected IECs through the secretion of anti-parasitic cytotoxic granules." (PMID 29295550, 2017). "While gene induction in adult DCs was higher than in cord DCs, broadly the same genes are induced in both cell types late in infection, with exception that in adult DCs a statistically significant increase in IFNG is seen." (PMID 28993767, 2017). "In case of R. typhi both either the cytotoxic activity or the release of IFNγ by CD8+ T cells is sufficient for protection while cytotoxicity seems to play a major role in the infection with other rickettsiae such as R. australis." (PMID 28770333, 2017). "Along with reduced pro-inflammatory cytokines, IL-1R−/− mice showed diminished levels of lung IFNγ compared to WT mice at the early (day 7) and late (days 14 and 21) phases of infection." (PMID 29403476, 2017). "IFNγ is the Th1 cytokine which gives protection in VL and generally down regulated during infection." (PMID 28646156, 2017). "We found mRNA expression of the Th1 transcription factor, T-bet, and the Th1 cytokine, IFNγ, to increase over the course of infection." (PMID 28103263, 2017). "The responses of IFNγ to aPPD differed at 30 and 60 dpi, but only increased by 0.2 in OD when compared with the pre-infection levels." (PMID 29145844, 2017). "To address how POP2 establishes control of infection while simultaneously encouraging a less inflammatory environment, we considered the potential contribution of IFNγ." (PMID 28580947, 2017). "A3Z1Tr was induced after SRLVs infection or stimulation of blood-derived macrophages with interferon gamma (IFN-γ)." (PMID 29149056, 2017). "The observation that still 70% of R. typhi-infected CB17 SCID mice that received IFNγ-/- CD4+ T cells survived the infection was surprising." (PMID 28222146, 2017). "As mentioned, IFNγ has a vital role in controlling early phase infection as a major component of the innate immune response." (PMID 29295550, 2017). "IFNγ was significantly increased in both infection groups compared to healthy controls (p = 0.038 in E. coli O104:H4 and p = 0.031 in E. coli O157:H7 infected animals, respectively)." (PMID 28559930, 2017). "The capability to produce or respond to interferon γ (IFNγ) is important in controlling infection by intracellular bacteria such as mycobacteria and Salmonella spp." (PMID 28804486, 2017). "On the other hand, elevated Ifnγ amounts during infection are important for the lower accumulation or survival of CD24hiCD3hi SP thymocytes." (PMID 28091621, 2017). "To characterize the mechanism of differential IL-17A and IFNγ expression between WT and IL-1RI−/− lungs, we identified the main sources of these cytokines after C. neoformans 52D infection." (PMID 29403476, 2017). "IFNγ production during S. pneumoniae infection is involved in the regulation of the neutrophil-mediated host defense against this infection." (PMID 28243234, 2017). "IL-6 is a pleiotropic cytokine secreted by a variety of cells in response to various stimuli, such as infections and other cytokines, including IL-1β, interferon gamma (IFN-γ), and TNF-α." (PMID 29233145, 2017). "Because Ccr2-/- mice also exhibited a profound defect in IL-12 production, we next examined secretion of IFNγ into the airway space of Ccr2-/- mice during infection." (PMID 28384349, 2017).
infection (continued). "In mice, infection due to Theiler’s Virus and Salmonella was controlled by lncRNA NeST by epigenetic regulation of interferon gamma IFNγ locus." (PMID 29657286, 2017). "For example, severity of infection, transplacental transmission, and interferon-gamma-induced antiparasitic effector mechanisms are similar in pigs and humans." (PMID 28883687, 2017). "We demonstrate here the localization of the chlamydial deubiquitinating enzyme Cdu1 to the inclusion surface and its essential role for chlamydial development in IFNγ-challenged cultured cells and in a mouse infection model." (PMID 28347402, 2017). "We have shown that IL-18 released in pathologically relevant situations, such as from epithelium after infection or from myeloid cells in lymphoid aggregates, has a spatially limited function with respect to its rapid innate regulation of IFNγ." (PMID 28830544, 2017). "Several Chlamydia studies have determined that interferon gamma (IFNγ)-producing CD4 T cells play a direct protective role during infection, as bactericidal IFNγ targets C.t. while it is intracellular." (PMID 28567043, 2017). "Overall, both cortisol and Ifnγ are important for the survival of most thymic subsets during infection." (PMID 28091621, 2017). "The frequency of BM CD4+ T cells capable of producing IFNγ within the total BM was very low (0.10% ± 0.05) in naive mice, but increased following infection (7.64% ± 3.57 of total BM cells)." (PMID 28671989, 2017). "Since the activation and subsequent differentiation of iMOs depends in part on STAT1 mediated IFNγ signaling, it is essential that we understand the role of this immune cell subset during infection with L. donovani." (PMID 29089636, 2017). "Similar observations were made for the infection of C57BL/6 IFNγ-/- mice with R. australis, a member of the transitional group." (PMID 28222146, 2017). "In turn, during pathogen infections, IL-12 produced by macrophages/monocytes and dendritic cells influences the production of interferon-gamma (IFN-γ) by natural killer (NK) and T cells, which favor phagocytic cells activation and inflammation." (PMID 29238325, 2017). "The IGRA measures interferon gamma response of the immune system to infection in blood samples using highly specific Mycobacterium tuberculosis antigens, thus providing improved specificity over TST." (PMID 28120106, 2017). "The most striking observation was that, the accumulation of DP3 thymocytes during infection was substantially reduced in Ifnγ−/− mice." (PMID 28091621, 2017). "The fold increase of IFNγ transcripts in the lungs after 24 h of infection was also significantly higher in WT mice compared to FHL2−/− mice." (PMID 28243234, 2017). "Upon infection, a modest decrease in Tnfα amounts was observed in Ifnγ−/− mice while serum cortisol amounts were comparable to those of infected BL/6 mice." (PMID 28091621, 2017). "The observation that Ifnγ induced upon infection inhibited the maturation of SP thymocytes is novel." (PMID 28091621, 2017). "Strikingly, Ccr2-/- mice also produced significantly less IFNγ at both 24 and 48 hours post-infection when compared to WT mice, in agreement with recent findings." (PMID 28384349, 2017). "Infant T cells are compromised in their capacity to regulate interferon gamma (IFN-γ), an important mediator in controlling viral and other intracellular pathogen infections." (PMID 28337207, 2017). "Our studies here used a systemic L. monocytogenes infection model to provide new experimental evidence in support of the model that type I IFNs exacerbate infection, at least in part, by suppressing macrophage responsiveness to IFNγ." (PMID 28542482, 2017). "In mice depleted of neutrophils with the more specific anti-Ly6G antibody, we also observed a significant decrease in IFNγ production at 72 hours post-infection compared to isotype-treated mice." (PMID 28384349, 2017).
infection (continued). "The behavior of WT, ΔaceA and complemented ΔaceA strains was similar during infection of both resting or IFNγ- and LPS-activated J774A.1 murine macrophage-like cells, under standard and microaerobic conditions." (PMID 28573107, 2017). "Given that SSM are an essential reservoir of IL-18 and that this cytokine was required for innate IFNγ responses in the dLN upon infection with lymph-borne bacteria, we investigated its role in our model." (PMID 29263880, 2017). "In fact, the release of IFNγ by CD8+ T cells was dispensable for defense against this infection because immune CD8+ IFNγ−/− T cells adoptively transferred into R. australis-infected C57BL/6 IFNγ−/− mice reduced the bacterial load and conferred protection." (PMID 28770333, 2017). "In another study, self-healing of the infection in mice correlated with the expansion of IFNγ and IL-17-producing CD4 cells, suggesting the existence of other active mechanisms to regulate local inflammation." (PMID 29163510, 2017). "Ifnar1−/− mice were infected with DENV2 strain S221, followed by detection of peptide-specific IFNγ-secreting CD3+ CD8+ T cells in the spleen via intracellular cytokine staining (ICS) assay on day 7 after infection." (PMID 29129917, 2017). "Meanwhile, the mRNA expression of Ifnα, Ifnβ, Ifnγ, Tnfα, and selective chemokines (Cxcl1, Cxcl2, and Ccl5) by leukocytes was lower in the blood of Ddx25-Tg mice on day 1 post-infection." (PMID 28824886, 2017). "We also show that granzyme A is elevated in CHIKV-infected NHPs and in CHIKV patients, with circulating granzyme A levels in NHPs peaking day 4–8 post infection, which coincides with the peak of circulating IFNγ levels." (PMID 28207896, 2017). "Interferon gamma plays essential roles in protective immunity against infections, particularly infections with viruses and intracellular bacteria and protozoan parasites." (PMID 28936213, 2017). "BFA addition during infection completely inhibited specific IFNγ secretion by the CHIKV 6K51-59 epitope-specific CD8+ T cell line, which demonstrated that this epitope was generated from CHIKV 6K protein endogenously processed in rVACV-CHIKV-infected cells." (PMID 29084215, 2017). "IL12Rβ1 deficiency and the consequent reduced IL-12 responsivity result in impaired production of IFNγ by NK cells and T cells, which impairs control of infection by mycobacteria and other intracellular bacteria." (PMID 28804486, 2017). "Extensive experimental data indicate that the autophagy machinery can promote killing of a broad variety of pathogens including T. gondii, especially in mouse models, and the IFNγ produced early in infection is crucial for that." (PMID 28955329, 2017). "mGBPs are highly induced via IFNγ after infection and are localized in intracellular vesicle-like structures." (PMID 28845089, 2017). "We also expected to find evidence of T-cell activation, and evidence of an IFNγ and TNFα response profile since patients present several weeks after primary infection, and long enough for T-cell and IFNγ responses to have developed." (PMID 29140996, 2017). "After adjusting for age, children in the middle/highest strata of Vδ2+ T cell IFNγ/TNF co-production had a significantly higher odds of submicroscopic infection if infected than children in the lowest strata (OR 1.46, 95% CI 1.01–2.11, P = 0.04)." (PMID 28904345, 2017). "Re-challenging these chronically infected mice with a high dose infection resulted in the induction of Muc2 and Il13 expression and a reduction in Ifnγ expression." (PMID 28192541, 2017). "A 2 to 6-fold increase in Ifnγ levels was also observed across the time course of infection in both NaS1 KO and wild-type mice although this did not significantly affect worm expulsion." (PMID 28192541, 2017). "Bacterial numbers were reduced in all CD4+IFNγ-/- T cell recipients including those that succumbed to the infection." (PMID 28222146, 2017).